CRP (C-reactive protein)
Diseases named in the same sentence as CRP in open-access papers (continued):
Sharing a sentence is not in itself a finding about the gene and the disease.
diabetes (continued). "The independent variables age, sex, presence of diabetes and hypertension, cigarette smoking, HDL, LDL, total cholesterol, hemoglobin, CRP, MHR and uric acid were utilized to determine risk factors associated with 30-day mortality in AIS patients." (PMID 36810474, 2023). "Male KTR in the highest tertile of plasma copper concentration also had more often diabetes (p = 0.01), higher hs-CRP (p < 0.001), and a lower SQUASH score (p = 0.007)." (PMID 36830012, 2023). "Included participants were younger, had lower levels of hypertension, diabetes, dyslipidemia, creatinine, hs-CRP, and pro-BNP, and less frequently reported a personal history of CVD." (PMID 34902049, 2023). "It was greater in participants with hypertension but unrelated to hyperlipidemia, hypertriglyceridemia, diabetes, elevated CRP, or obesity." (PMID 37693005, 2023). "In conclusion, the consumption of fish oil supplements was linked to decreased serum CRP and VLDL-C levels and subsequent CHD risk among adults with prediabetes and diabetes." (PMID 37513593, 2023). "In the general population, CRP levels are higher in females than males, even when stratified by BMI or adjusted for age, ethnicity, diabetes, hypertension, smoking, and alcohol consumption." (PMID 38003780, 2023). "In both reactivation and coinfection groups, patients reported cardiovascular disease, diabetes, and immunosuppression as comorbidities, acute kidney injury as complication, and lymphopenia and elevated D-dimer and CRP levels from blood tests." (PMID 37101275, 2023). "The associations were mainly mediated by CRP in participants with prediabetes and VLDL-C in patients with diabetes." (PMID 37513593, 2023). "Adiponectin has shown to negatively correlate with highly sensitive CRP in patients with diabetes and was also shown to inversely correlate with CRP levels following the BNT162b2 vaccine in SARS-CoV-2 infected individuals." (PMID 37676889, 2023). "Specifically, crude estimates suggest that the proportion of individuals developing diabetes/high blood glucose was approximately 16.85% in the low wealth/elevated CRP group compared to 5.37% in the high wealth/low CRP reference group." (PMID 37808231, 2023). "Four models were evaluated where either baseline LVEF, IS, MVO or IMH were regarded as the dependent variable, and GSDMD, IL-1β, CtnI, diabetes, CRP and anterior infarction localization as independent variables." (PMID 37424923, 2023). "The variables are age ≥69 years, CRP (above level), troponin I (above level), shock, pulmonary edema, dysrhythmia, diabetes with complications, anemia, and respiratory infection." (PMID 36844231, 2023). "After further adjustment for covariables ofBMI, CRP, diabetes, emergency operation, NYHA III–IV, and left atrial diameterin Model 3, the higher VAI, VATI and TyG index were significantly associated withan increased risk of POAF." (PMID 39076438, 2023). "The presence of both low wealth and elevated CRP was implicated in the onset of CHD, stroke, diabetes/high blood glucose, and cardiometabolic multimorbidity up to 14 years later, reflecting the role of psychobiological processes in predicting disease burden." (PMID 37808231, 2023). "Additional secondary analyses examined the multiplicative effect of CRP on the relationship between wealth and incident diabetes/high blood glucose, CHD and stroke." (PMID 37808231, 2023). "The most important findings were the differences in the KP between the Healthy group and the groups with a disease, and the influence of the covariates BMI, smoking, diabetes, and CRP on the KP." (PMID 36986451, 2023). "CRP is an indicator of chronic inflammation which can raise in many disorders such as diabetes, CVD, and metabolic syndrome." (PMID 36627587, 2023). "Significant differences in FPG, homocysteine (HCY), high-sensitivity C-reactive protein (hs-CRP), alcohol consumption, and diabetes mellitus were observed among the groups with different HbA1c levels." (PMID 36949414, 2023).
diabetes (continued). "In the current study, we observed a strong correlation between CRP concentrations and both body weight and BMI, which was even more apparent in the group with diabetes at equivalent weights and BMI." (PMID 37891943, 2023). "Patients with noncalcified plaques exhibited higher total cholesterol, LDL, and CRP levels, along with a trend toward increased diabetes mellitus." (PMID 37736993, 2023). "Multivariate regression analysis showed that duration of diabetes, HbA1c, TcPO2, CRP, and eGFR were independent factors influencing the occurrence of foot ulcers, which were consistent with previous findings." (PMID 36829206, 2023). "We included the following factors in the logistic regression model as important: Gender, Hypertension, AKI, Treatment with Remdesivir, Febrile, CKD, age, IL-6, CRP, uNGAL, uKIM-1, Diabetes, and Proteinuria." (PMID 36983566, 2023). "Logistic regression model results of BP and BPV estimating diabetes, obesity, and CRP unweighted data." (PMID 37693005, 2023). "Hypervolemic patients were older, more frequently had diabetes and showed increased CRP and IL-6 levels." (PMID 38139378, 2023). "The most significant predictors for a lethal outcome according to multivariate analysis were diabetes mellitus (p < 0.001) followed by a subsequent elevation in C-reactive protein levels (CRP; p < 0.002) and ferritin (p < 0.013) after Tocilizumab application." (PMID 38034537, 2023). "Our finding is noteworthy because we adjusted for many known risk factors to assess mortality risk, such as age, anemia, diabetes, history of CAD, high CRP level, and volume overload status, over a long duration." (PMID 37432308, 2023). "The factors associated with the increased frailty levels in our patients included older age, low BMI, low serum albumin, high CRP, the comorbidity of diabetes and cardiovascular diseases, and the history of fractures, which were consistent with prior studies." (PMID 37696942, 2023). "Uncontrolled diabetes, the severity of the COVID-19 infection at presentation, acidosis, a high C-reactive protein level (above 100) and local brain involvement were associated with a poor outcome." (PMID 36312629, 2022). "These individuals had a higher percentage of CVD family history, while featured lower SBP, FPG, and hs-CRP level and lower prevalence of hypertension, diabetes, and the proportion of medical treatment compared with those who had an older onset age." (PMID 35370968, 2022). "Some evidence indicates the role of CRP in diabetes-induced microvascular complications, such as neuropathy, retinopathy, and nephropathy." (PMID 35620114, 2022). "Model 3 added to model 2 the education level, income to poverty ratio, marital status, smoking status, vigorous recreational activity, BMI, CRP, stroke, cancer, diabetes, CVD, energy, and uric acid as covariates." (PMID 36311643, 2022). "The inflammatory marker CRP is even considered as a predictor for pre-diabetes, diabetes and fatty liver disease." (PMID 35440685, 2022). "Diabetes history, overweight, and elevated C-reactive protein were more frequently observed among patients with retinal abnormalities, while a history of systemic hypertension was more frequently observed among patients without retinal findings." (PMID 35407441, 2022). "Global CT score, age, C-reactive protein, and diabetes were independent predictors of in-hospital mortality." (PMID 36004961, 2022). "Multivariate regression analysis showed that the CONUT score was independently correlated with age (β = 0.025, p = 0.03), diabetes mellitus (β = 0.695, p = 0.009), CRP (β = 0.485, p < 0.0001), and hemoglobin (β = −0.578, p < 0.0001)." (PMID 35684116, 2022). "As well, the median of CRP in women having diabetes was significantly higher (0.69 mg/dL) than in women free of diabetes (0.26 mg/dL)." (PMID 34991564, 2022).
diabetes (continued). "sedentary group is in line with previous studies, which suggested that patients with elevated levels of CRP and pro-inflammatory cytokines such as TNF-α, IL-6 are at increased risk of diabetes, atherosclerosis, hypertension and other cardiovascular diseases." (PMID 36434695, 2022). "AA/DHAA have also been reported to influence C-reactive protein levels and protein glycation, prompting further investigation into A. mexicanus as a model of diabetes-related resilience." (PMID 35703366, 2022). "Because it is primarily understood as an inflammatory marker, GlycA was related to CRP and partly also to IL-6 in the context of diabetes mellitus and in prediction models of cardiovascular incidents, where it proved to have considerable expressive power." (PMID 36557315, 2022). "It is interesting that the hs-CRP levels during follow-up (≥6 month) were substantially related to an elevated risk of ISR after we adjusted for age, follow-up time, and diabetes." (PMID 36005411, 2022). "To further evaluate the effect of disease-dependent biomarkers such as A1c, we performed KDM analysis in prediabetes and diabetes population excluding A1c and including CRP." (PMID 34773197, 2022). "Previous research found that increased age, male gender, increased CRP, and comorbid conditions (mainly malignancy, congestive heart failure, diabetes mellitus, and renal disease) act as predictive factors for mortality in patients hospitalized with CAP." (PMID 35453219, 2022). "While it is known that inflammation plays a role in type 2 diabetes mellitus, recent data suggest that inflammation indexed by CRP precedes progression to type 2 diabetes." (PMID 35757631, 2022). "Compared with Q1–Q3, participants in the Q4 tended to be older, have higher BMI, SBP, DBP, cum-TyG index, poorer metabolic profile (FBG, TG, LDL-C and hs-CRP), and with higher prevalence of hypertension and diabetes (P < 0.01)." (PMID 35505313, 2022). "In univariate cox regression models, CV-mortality was associated with age, diabetes mellitus, serum creatinine, albumin, total cholesterol, LDL-cholesterol, triglycerides, CRP, GNRI, and CI." (PMID 36326327, 2022). "Other factors significantly associated with increased mortality were older age, female sex, diabetes mellitus, heart failure, lower body mass index and higher C-reactive protein levels." (PMID 35902805, 2022). "Although the clinical relationship between diabetes and increased level of CRP is well established, the molecular mechanisms by which CRP potentially induces diabetes are yet to be clarified." (PMID 35620114, 2022). "In the context of diabetes, obesity and coronary artery disease, adiponectin is lower in cases than controls and inversely correlated with C-reactive protein (CRP) levels." (PMID 35317720, 2022). "In attempting to explain variance in mREE better, the MHDE REE includes increased metabolic expenditure for clinical factors such as inflammation (CRP), diabetes status (A1c), and muscle catabolism (SCr)." (PMID 35356849, 2022). "Older adults in the United States have a much higher prevalence of diabetes, low high-density lipoprotein cholesterol, and high inflammation (C-reactive protein) compared to English adults." (PMID 35217868, 2022). "The OR was 0.62 (95%CI 0.39, 0.98) in the fully-adjusted model (Model 4), which adjusted for age, CT type, hypercholesterolemia, diabetes, hypertension, pack-year of smoking, ethanol, obesity, eGFR, CRP, and TG." (PMID 36418419, 2022). "The multivariate linear regression for the BMI revealed a significant relationship between BMI and diabetes mellitus, glycosylated Hb, mean blood pressure, Hb, the CRP log, and uric acid." (PMID 35628912, 2022). "At the same time, considering some other variables in AMI such as diabetes, CRP and hypertension, we analyzed the correlation between GSDMD expression level and them." (PMID 36544106, 2022).
diabetes (continued). "The higher level of CRP was only partially explained by a higher prevalence of smoking, diabetes mellitus, and obesity in that group." (PMID 36304737, 2022). "In this study, age, fever, hemoptysis, shortness of breath, hypertension, cardiovascular, diabetes, glucocorticoid, immunoglobulin, HFNC, disease severity, HGB, CRP, ESR and ALB were risk factors for PF, which was in according with previous studies." (PMID 36619759, 2022). "Compared with patients with BMI <25 kg/m2, more patients with BMI ≥ 25 kg/m2 had diabetes, MS, and a higher BMI, waist circumference, mean BP, eGFR, hemoglobin level, CRP level, and triglyceride level." (PMID 36185692, 2022). "In the health survey of the subjects themselves, the patients themselves were suffering from hypertension, diabetes, hyperlipidemia, high myopia, chronic pain, and abnormal CRP index in the blood analysis." (PMID 35566498, 2022). "We examined age, body mass index, diabetes, an existing diagnosis of diabetes, fasting blood glucose, left-ventricular ejection fraction, aortic valve mean gradient, C-reactive protein levels, and serum creatinine levels." (PMID 36676003, 2022). "Diabetes-related metabolic traits can include glucose, hemoglobin A1c (HbA1c), C-reactive protein (CRP), body mass index (BMI), cholesterols, and blood pressure (BP)." (PMID 35356427, 2022). "Decreased muscle strength is related to increased levels of inflammatory markers (tumour necrosis factor-alpha (TNF-α), interleukin-6 (IL-6), and C-reactive protein (CRP)), which can induce the development of diabetes." (PMID 36010223, 2022). "We also found several other factors that were associated with higher mortality rates and more complications, including older age, female sex, diabetes, heart failure, increasing CRP levels and lower BMI." (PMID 35902805, 2022). "The exclusion of participants with hs-CRP ≥ 10 mg/l (n = 67) or the exclusion of participants with cancer in active treatment, diagnosis of diabetes and treatment of CVD within a year in both time points (n = 1000) did not affect the results of main analyses." (PMID 35260816, 2022). "In the current study, among participants with type 2 diabetes, we found that unfavorable CVH was related to a higher CRP level, which in turn was related to a higher development of diabetes complications and mortality." (PMID 36307875, 2022). "In summary, a simple scoring system was constructed with a combination of five variables: diabetes mellitus, chills, CRP (50–100 mg/L), PCT (> 0.3 ng/mL), and neutrophil percentage (> 75%) in the cohort of 712 FUO patients." (PMID 36482449, 2022). "Patients were older and had more pronounced cardiometabolic profile as reflected by their hypertension, dyslipidemia, diabetes, and increased waist-hip ratio, c-reactive protein (CRP) and leukocyte counts." (PMID 36572703, 2022). "Compare the BPV with inflammation marker (Hs-CRP) tostudy the impact of the effect of BPV in patients with diabetes onvascular endothelium cells using 24-hour ABPM." (PMID 35584515, 2022). "In total, nine variables were included in the model (age, sex, immunocompromised status, Charlson Comorbidity Index, diabetes, COVID-19 infection, CRP, WBC, and PSP)." (PMID 35631080, 2022). "A predictive model incorporating C-reactive protein, lactate dehydrogenase, and diabetes status at the time of admission predicted intubation status with an area under the curve (AUC) of 0.78 with corresponding sensitivity of 86%, specificity of 63%." (PMID 35274051, 2022). "In a predictive model, a high C-reactive protein, lactate dehydrogenase and presence of diabetes mellitus predicted the need for intubation, with high sensitivity and moderate specificity." (PMID 35274051, 2022). "As expected, higher serum hs-CRP coincided with a higher prevalence of diabetes, hypertension, and higher levels of BMI, platelet, FPG, HBA1c, and HOMA-IR scores." (PMID 36338499, 2022).
diabetes (continued). "Medical records, including data on diabetes mellitus status, delta neutrophil index values, white blood cell count, polymorphonuclear leukocyte count, erythrocyte sedimentation rate, and C-reactive protein level, were retrospectively investigated." (PMID 35926065, 2022). "After adjusting for age, diabetes duration, retinopathy, C-reactive protein, albumin, creatinine, and procalcitonin, a logistic regression analysis identified only age and albumin as independent predictors of death." (PMID 36588684, 2022). "Consistent with previous findings, CRP, an indicator of systemic inflammation, was correlated with diabetes markers." (PMID 36687728, 2022). "In the final multivariable model, age > 75 years, active smoking, diabetes mellitus, elevated CRP ≥ 15 mg/L, and CA 19-9 > 500 U/ml were confirmed as independent risk factors for early mortality after upfront surgery due to PDAC." (PMID 35939088, 2022). "Socio-demographics (age, sex, ethnicity), hypertension, diabetes, obesity, baseline physiological observations, CRP, neutrophil, chest x-ray abnormality, remdesivir and dexamethasone were incorporated as co-variates." (PMID 35025917, 2022). "When adjusted for CRP (as a marker of systemic inflammation), both pre-diabetes and diabetes mellitus accounted for an increase of 19% and 37% in plasma NfL levels (adjusted model 2)." (PMID 35795150, 2022). "For instance, genetic variables for diabetes, higher plasmatic CRP, vitamin D or n3-PUFA or BMI did not lead to an increased risk for MDD." (PMID 36354137, 2022). "A recent study found that the presence of diabetes mellitus, low left ventricular ejection fraction, increased baseline high sensitivity CRP, and low baseline Th2 cell counts were significant predictors of death following TAVI." (PMID 36676003, 2022). "On multivariable analyses, hypertension and diabetes were independent risk factors for ICAS of both AC and PC, while hyperlipidemia and elevated hi-CRP were independently associated with PC lesions." (PMID 35047049, 2022). "The clinical assumption is, however, that CRP and complete blood counts are measured based on suspicion of infection, due to other chronic diseases like hypertension and diabetes with regular blood workup or as a routine check." (PMID 35603299, 2022). "Inflammatory components (CRP, endocan and perfusion index) exhibited a statistically significant (p ≤ 0.05) positive correlation in subjects with dengue with diabetes." (PMID 36268329, 2022). "Serum concentrations of acute phase proteins such as sialic acid, glycoprotein A-1, CRP and amyloid A, and cortisol have been shown to be high in diabetes." (PMID 35178206, 2022). "Group 1 was characterized by older age, higher prevalence of diabetes, lower nPCR, higher Davies score and hs-CRP level." (PMID 36346823, 2022). "The univariate analyses confirmed multiple known demographic, clinical, and laboratory mortality risk factors of HD patients, such as male gender, advanced age, diabetes, history of cardiovascular diseases, and CRP concentrations." (PMID 36143124, 2022). "At baseline, CRP correlated significantly (p < 0.001) with all metabolic indexes in women (dyslipidemia, hypertension, and diabetes), but less so than in men." (PMID 36304737, 2022). "Multivariable analyses adjusted for age, serum CRP level, and diabetes mellitus showed that high serum levels of TIMP-1 were independently related to a diagnosis of motor neuropathy in MPA." (PMID 36362162, 2022). "Several findings have shown incidence of diabetes following high levels of IL6 among other markers such as CRP." (PMID 36561566, 2022). "Serum CRP and Endocan levels showed strong while perfusion index showed intermittent positive relationship with the dengue with diabetes group." (PMID 36268329, 2022).